FADS2 (fatty acid desaturase 2)
Description:
Involved in the biosynthesis of highly unsaturated fatty acids (HUFA) from the essential polyunsaturated fatty acids (PUFA) linoleic acid (LA) (18:2n-6) and alpha-linolenic acid (ALA) (18:3n-3) precursors, acting as a fatty acyl-coenzyme A (CoA) desaturase that introduces a cis double bond at carbon 6 of the fatty acyl chain. Catalyzes the first and rate limiting step in this pathway which is the desaturation of LA (18:2n-6) and ALA (18:3n-3) into gamma-linoleate (GLA) (18:3n-6) and stearidonate (18:4n-3), respectively. Subsequently, in the biosynthetic pathway of HUFA n-3 series, it desaturates tetracosapentaenoate (24:5n-3) to tetracosahexaenoate (24:6n-3), which is then converted to docosahexaenoate (DHA)(22:6n-3), an important lipid for nervous system function (By similarity). Desaturates hexadecanate (palmitate) to produce 6Z-hexadecenoate (sapienate), a fatty acid unique to humans and major component of human sebum, that has been implicated in the development of acne and may have potent antibacterial activity. It can also desaturate (11E)-octadecenoate (trans-vaccenoate, the predominant trans fatty acid in human milk) at carbon 6 generating (6Z,11E)-octadecadienoate (By similarity). In addition to Delta-6 activity, this enzyme exhibits Delta-8 activity with slight biases toward n-3 fatty acyl-CoA substrates (By similarity).
Synonyms: D6D; FADSD6; TU13; DES6; SLL0262; LLCDL2
Tractability: Antibody: its Gene Ontology location is reachable by antibodies, with high confidence; UniProt predicts a signal peptide or a membrane-spanning region; the Human Protein Atlas places it where antibodies can reach. PROTAC: ubiquitination databases record sites on it; its protein half-life has been measured.
Target class: Enzyme; Oxidoreductase
Gene: Protein-coding gene on chromosome 11 (61,792,980 to 61,867,354, forward strand). Ensembl gene ENSG00000134824.
Subcellular location: Endoplasmic reticulum membrane
Subcellular location (Human Protein Atlas): Endoplasmic reticulum; Nuclear membrane; Plasma membrane
Pathways (Reactome):
Metabolism: Linoleic acid (LA) metabolism; alpha-linolenic acid (ALA) metabolism
Gene Ontology:
Molecular function: acyl-CoA 6-desaturase activity; acyl-CoA desaturase activity; oxidoreductase activity; stearoyl-CoA 9-desaturase activity
Biological process: alpha-linolenic acid metabolic process; linoleic acid metabolic process; unsaturated fatty acid biosynthetic process; arachidonate metabolite production involved in inflammatory response; fatty acid biosynthetic process; lipid metabolic process; positive regulation of cellular response to oxidative stress
Cellular component: membrane; endoplasmic reticulum membrane; plasma membrane
Genetic constraint (gnomAD): Loss-of-function variants: 17 observed, 61.41 expected, observed/expected ratio (o/e) 0.28, 90% interval 0.19 to 0.41. The upper end of that interval is the gene's LOEUF score, 0.41, which puts it in group 1 of 6, group 1 being the genes least tolerant of losing a copy. Missense variants: 319 observed, 595.44 expected, observed/expected ratio (o/e) 0.54, 90% interval 0.49 to 0.59. Synonymous variants: 203 observed, 233.27 expected, observed/expected ratio (o/e) 0.87, 90% interval 0.77 to 0.98.
Homologues: Orthologues: chimpanzee FADS2 (100% identical), rabbit FADS2 (91% identical), dog FADS2 (90% identical), rat Fads2 (88% identical), mouse Fads2 (88% identical), macaque FADS2 (86% identical), pig FADS2 (84% identical), guinea pig FADS2 (81% identical), tropical clawed frog fads2 (71% identical), zebrafish fads2 (65% identical), Caenorhabditis elegans fat-4 (26% identical), Caenorhabditis elegans fat-3 (26% identical). Paralogues in human: FADS3 (63% identical), FADS1 (62% identical), FADS6 (16% identical).
Diseases named in the same sentence as FADS2 in open-access papers:
FADS2 is named in the same sentence as 163 diseases in open-access papers, as found by Europe PMC text mining. Sharing a sentence is not in itself a finding about the gene and the disease. The quoted sentences say what the papers report.
Obesity (41 papers, 2013 to 2025). Accumulation of substantial excess body fat. "FA desaturase (FADS1 and FADS2) polymorphisms are associated with Alzheimer’s disease, Acute Coronary Syndrome, Autism spectrum disorder and obesity." (PMID 36900123, 2023). "Minor alleles of various FADS1 (rs174545, rs174546, rs174548, and rs174553) and FADS2 (rs1535 and rs174583) genes have been associated with an increased risk of obesity in women with a lower BMI (less than 25.0 kg·m−2)." (PMID 35736500, 2022). "There was a direct positive association between the markers of obesity and FADS2 activity and an inverse association with FADS1 in a Swedish study, with relationships being independent of body mass index and physical activity." (PMID 36712514, 2022). "The role of fatty acid desaturase 2 genetic variants in promoting obesity and obesity-related disorders like insulin resistance and dyslipidemia is reported in previous studies." (PMID 35773659, 2022). "In this concept, considering the effect of interaction between fatty acid desaturase 2 (FADS2) gene variants and dietary advanced glycation end products (AGEs) on obesity-related characteristics seems to be challenging." (PMID 34611217, 2021). "Single nucleotide polymorphisms (SNPs) in FADS genes are with race- and ethnic-specific distributions and associated with levels of circulating LC-PUFA, and several SNPs in FADS1/FADS2 have been linked with a risk of overweight and obesity." (PMID 33494132, 2021). "Our study examined a link between habitual polyphenol intake, levels of LC-PUFA, and obesity parameters in adult subjects, and depending on the variant allele presence within the three FADS2 SNPs (rs174593, rs174616, and rs174576)." (PMID 33494132, 2021). "In conclusion, minor allele carriers of FADS1 and FADS2 SNPs have an increased risk of obesity (p≤0.05)." (PMID 28598979, 2017). "The Δ6-desaturase (Δ6D), also known as fatty acid desaturase 2, is a regulatory enzyme in de novo fatty acid synthesis, which has been linked to obesity and diabetes." (PMID 24294133, 2013). "Another case–control studyreported an association between FADS1/rs174556,FADS2/rs174617, and obesity, by demonstrating that plasmalevels of omega-6 PUFAs and AA were higher in overweight and obese patients;however, the difference in ω-3 PUFA levels was not significant." (PMID 39076540, 2024). "Genetic variations in the FADS2 gene has been associated with several traits related to obesity and cardiometabolic health, including fatty acid metabolism and adipose tissue inflammation, leading to an interaction between weight loss and FADS2 genes in the regulation of adipose tissue inflammation." (PMID 34165540, 2021). "The lipid changes observed in our metabolomic data may be related to those observed in FADS2-deficient mice, which in turn are obesity-resistant." (PMID 27589269, 2016). "In line with the demonstrated relationships between FADS2 make-up in the three genetic variants and LC-PUFAs in plasma phospholipids, we further examined whether the changes in the fatty acids affect changes in the obesity parameters." (PMID 33494132, 2021). "Moreover, FADS2-deficient mice are resistant to obesity and the dysregulation of lipogenesis." (PMID 25887532, 2015). "In the adrenal glands, FADS2 activity determines proper corticosteroid synthesis; its deficiency impairs mitochondrial structure and reduces hormone levels, while in obesity, increased FADS2 expression promotes excessive corticosterone production." (PMID 41002979, 2025). "Accordingly, pharmacological inhibition of FADS2 reduces corticoid production in mice with established obesity." (PMID 40551885, 2025). "To validate the role of FADS2 in adrenocortical steroidogenesis in obesity, we treated HFD mice with the FADS2 inhibitor SC-26196 and assessed corticosteroid production." (PMID 37478183, 2023).
Obesity (continued). "It is known that the FA metabolism changes in obesity: the desaturating enzyme activity of FADS2 appeared to increase while that of FADS1 appeared to be inhibited with the result of lower LCPUFA levels." (PMID 35177087, 2022). "FADS2 is related to many chronic diseases, including obesity, type 2 diabetes and metabolic abnormalities." (PMID 34418989, 2021). "These SNPs were located mainly in genes related to atherosclerosis and obesity such as FADS2 (rs174577 and rs174589), GATA 2 (rs3803) and TFAP2B (rs2272903)." (PMID 27589269, 2016). "Desaturation can be catalyzed by SCD1 or FADS2 molecules, known to play a role in obesity and inflammatory diseases." (PMID 24695116, 2014). "Having found that the adrenal lipidome is integral to the regulation of steroidogenesis, we next asked whether it can be modulated in established obesity by FADS2 inhibition." (PMID 37478183, 2023). "Fads2 expression in the adrenal medulla increased with obesity." (PMID 37478183, 2023). "The FADS2 polymorphisms are associated with LC-PUFA metabolism and overweight/obesity." (PMID 33494132, 2021). "Analysis of Fads2 -/- mice (another endogenous PUFA deprived model system) also revealed an obesity resistance phenotype that, upon DHA treatment, resulted in hyperphagia together with increased body weight as well as enlarged white adipose tissue mass and size of adipocytes." (PMID 30991731, 2019). "Furthermore, knockout- (KO-) Fads2 mice develop obesity resistance and impaired lipogenesis." (PMID 34956370, 2021). "Moreover, altered DNA methylation of several genes has been associated with obesity, type II diabetes, and NASH, but the role of FADS2 DNA methylation in NAFLD is unknown." (PMID 30654845, 2019). "The results showed that potential intermediates between omega-3 fatty acids or FADS1/FADS2 genes and cognitive function were mostly associated with metabolic or neurological diseases, such as non-insulin dependent diabetes, metabolic syndrome, obesity and Alzheimer’s disease." (PMID 38316767, 2024). "Accordingly, this study with a new gene-nutrient approach, can provide a better perspective of dietary interventions and it is of interest that whether FADS2 gene polymorphism and dietary AGEs content might affect obesity-related risk-traits together which has not been assessed before." (PMID 34611217, 2021). "Fatty acid desaturase 2 (FADS2), the rate-limiting enzyme of PUFA synthesis, is highly expressed in the adrenal gland and is upregulated in conditions of elevated corticoid synthesis, such as obesity or adrenal adenomas." (PMID 40551885, 2025). "Genetic variation, particularly in the FADS1, FADS2, and ELOVL2 genes, may significantly influence FA metabolism and the development of metabolic disorders such as obesity." (PMID 41002979, 2025). "Similarly, a growing number of studies demonstrated a positive correlation between increased FADS2 expression and IR as well as TD2M occurrence, whereas FADS2 inhibition resulted in resistance to HFD-induced obesity in a mouse model." (PMID 36879113, 2023). "SNPs of FADS2 (rs174593, rs174616, and rs175576) have been documented to play a role in the interaction of polyphenols with PUFA levels and parameters of obesity, while lower levels of TC, LDL-C, and HDL-C have been associated with the minor allele of FADS1 rs174547." (PMID 35736500, 2022). "DNA methylation levels in the CpG sites annotated to FADS2 and FADS1 were analyzed from liver samples of 95 obese participants of the Kuopio Obesity Surgery Study (34 men and 61 women, age 49.5 ± 7.7 years, BMI 43.0 ± 5.7 kg/m2) using the Infinium HumanMethylation450 BeadChip (Illumina)." (PMID 30654845, 2019).
Obesity (continued). "Additionally, numerous identified mQTL-SNPs cover previously identified GWAS loci for obesity, lipid and diabetes related traits e.g. POMC, GIPR, GRB10, FADS2, SORT1 and APOA5." (PMID 27322064, 2016). "Particularly, lowering the AA content of phospholipids through regulation of FADS2 by dietary adjuncts, such as icosapent ethyl, could be a novel strategy to regulate moderately elevated corticoid production in obesity, a concept which merits clinical investigation." (PMID 40551885, 2025).
breast carcinoma (21 papers, 2013 to 2025). "Recently, a report showed that FADS1 compensated for the functions of FADS2 on twenty-carbon fatty acids under FADS2-deficient conditions such as MCF-7 breast cancer cell conditions." (PMID 26742061, 2016). "For example, mutations in FADS2 has been reported in tumors from breast cancer patients and the loss of expression of FADS2 was significantly associated with aggressive tumor phenotype and reduced survival." (PMID 24027672, 2013). "The FADS2 activity associated with the aromatase drug letrozole in breast cancer cells." (PMID 34900981, 2021). "Secondly, considering the promoting effect of SCD1 and FADS2 on breast cancer development, how to combine these inhibitors to promote the therapeutic effect of existing chemotherapy drugs is a question worth exploring." (PMID 38905386, 2024). "FADS2 expression of breast cancer had a positive relationship with almost all tumor biological behaviors, such as inflammation, cell cycle, DNA repair response, proliferation, differentiation, and DNA damage." (PMID 36788618, 2023). "FADS2 expression profiles were demonstrated at single-cell levels from glioma, skin melanoma, and breast cancer by T-SNE diagram." (PMID 36788618, 2023). "SCD1 and FADS2 are responsible for biosynthesis of monounsaturated fatty acids to inhibit ferroptosis in ovarian and breast cancer cells." (PMID 36130940, 2022). "Recent studies showed that FADS2 has a high expression level in breast cancer tissues and esophageal squamous cell carcinoma, which plays a vital role in the occurrence and development of these cancers." (PMID 35401213, 2022). "Lower FADS2 expression levels are significantly correlated with a poor prognosis during human breast cancer." (PMID 34095228, 2021). "Our online search identified 4 SNPs — rs1800562 in HFE, rs174577 in FADS2, rs651007 in ABO and rs4921915 in NAT2 — related to LDL-C, TCHO, and/or TG levels, which have been reported to influence breast cancer risk." (PMID 34229617, 2021). "For this reason, the expression of FADS1 and FADS2 is increased in some cancers, e.g., Lewis lung carcinoma, melanoma, colon cancer, hepatocellular carcinoma, and breast cancer." (PMID 32392704, 2020). "FADS2 has also been found to be overexpressed in breast cancer." (PMID 40403013, 2025). "Similarly, FADS2 is highly expressed in breast cancer, and its knockout reduces cell invasion, migration, and colony formation." (PMID 40430008, 2025). "It has been found that FADS2 was abnormally expressed in liver cancer, glioblastoma, lung cancer and breast cancer, which may be an important biomarker of tumor metabolic reprogramming." (PMID 34790227, 2021). "In human breast cancer MCF7 cells, loss of FADS2 function blocks normal polyunsaturated fatty acid biosynthesis resulting in the FADS1 generation of polyunsaturated fatty acids which lack the 8–9 double bond of eicosanoid signaling precursors (i.e., arachidonic acid and eicosapentaenoic acid)." (PMID 26445145, 2015). "Therefore, investigating the interplay between omega-3 supplementation and FADS1/FADS2 genotypes in breast cancer could provide valuable insights into personalized dietary interventions and therapeutic strategies." (PMID 40430008, 2025). "Herein, taking into account that leptin induces SREBP‐1 in MCF‐7 breast cancer, we have identified SREBP‐1 target genes in response to leptin stimulation, including FASN, ACLY, and FADS2." (PMID 33226729, 2021). "In turn, FADS2 displayed oncogenic properties in B16 melanoma, LLC Lewis lung carcinoma, MCF7 cell line (breast cancer), and HT-29 human colon cancer cells." (PMID 32392704, 2020). "We demonstrated that SCD1 and FADS2 could be potential biomarkers to predict or diagnose aggressive breast cancer, and the SCD1 or FADS2 expression is positively related to infiltration of immune cells in tumor microenvironment." (PMID 38905386, 2024).
breast carcinoma (continued). "Breast tumors and breast cancer cell lines have reduced levels of delta-6 desaturase (FADS2) compared to non-malignant cells, as is delta-5 desaturase (FADS1) in non-small-cell lung cancer and esophageal squamous cell carcinoma." (PMID 33413672, 2021).
diabetes (19 papers, 2013 to 2025). "The study results potentiate the functional link between FADS2 gene polymorphism, lipid levels and type-2 diabetes mellitus." (PMID 34162950, 2021). "Haplotype reconstruction may be of particular importance in studies looking at insulin resistance measures or diabetes risk as D5D (FADS1) and D6D (FADS2) activities have been shown to have an opposite relationship with diabetes risk." (PMID 24455201, 2013). "A recent systematic review showed that the relationship between PUFA intake, individual FA serum levels and diabetes risk is linked to polymorphisms of the genes expressing D5D and D6D (FADS1 and FADS2, respectively)." (PMID 30400149, 2018). "Alterations to the activity of the FADS2 and FADS1 gene products, delta-6 and delta-5 desaturase, respectively, has been associated with several diseases, such as diabetes, cardiovascular disease, inflammation, and cancer (breast, melanoma, lung)." (PMID 28506205, 2017). "High FADS2 activity (Δ6-desaturase) and low FADS1 (Δ5-desaturase) activity have been associated with insulin resistance and, most importantly, have been shown to predict the development of diabetes." (PMID 41007350, 2025).